SIX4 (SIX homeobox 4)
Diseases named in the same sentence as SIX4 in open-access papers (continued):
Sharing a sentence is not in itself a finding about the gene and the disease.
osteosarcoma (2 papers, 2023 to 2024). A usually aggressive malignant bone-forming mesenchymal neoplasm, predominantly affecting adolescents and young adults. "To explore whether SIX4‐mediated osteosarcoma metastasis is associated with upregulation of IDH1, we examined the expression of IDH1 in SIX4 overexpression and knockdown cells." (PMID 36601689, 2023). "To understand whether SIX4‐mediated osteosarcoma metastasis is associated with glycolysis, we examined the extracellular acidification rate/oxygen consumption rate (ECAR/OCR)." (PMID 36601689, 2023). "The upregulation of SIX4 mRNA and protein was further validated in fresh samples from surgery patients of osteosarcoma." (PMID 36601689, 2023). "Taken together, these results demonstrated that IDH1 knockdown significantly suppressed the SIX4‐driven metastasis of osteosarcoma." (PMID 36601689, 2023). "In summary, combined with the public data and our results, we demonstrated that upregulation of SIX4 in osteosarcoma is important for metastasis and poor prognosis." (PMID 36601689, 2023). "In this study, we demonstrated that overexpression of SIX4 promoted osteosarcoma metastasis by changing glycolysis and upregulating isocitrate dehydrogenase 1(IDH1) expression." (PMID 36601689, 2023). "We found that SIX4 is significantly overexpressed in osteosarcoma and related to the undesirable prognosis of osteosarcoma patients." (PMID 36601689, 2023). "In conclusion, our study found that SIX4 promotes progression of osteosarcoma via upregulating IDH1 and metabolic reprogramming, which provides novel prognostic biomarkers and promising therapeutic targets for osteosarcoma patients." (PMID 36601689, 2023). "All these findings demonstrated that SIX4 promoted osteosarcoma progression via regulating tumour cell glycolysis." (PMID 36601689, 2023). "Consistently, the SIX4 mRNA and protein expression were upregulated in osteosarcoma cell lines compared with the bone cell line hFOB1.19." (PMID 36601689, 2023). "To better understand the role of SIX4 in osteosarcoma, we evaluated the SIX4 expression in human osteosarcoma cell lines (U2OS, 143B, MNNGHOS, MG63, G292), as well as bone cell line (hFOB1.19)." (PMID 36601689, 2023). "Given the significance of SIX4 in carcinogenesis and metabolic reprogramming, we test the expression of SIX4 in osteosarcoma tissues and cell lines." (PMID 36601689, 2023). "Our results showed that SIX4 was upregulated in osteosarcoma, and its upregulation predicted poor outcomes for osteosarcoma." (PMID 36601689, 2023). "Collectively, these results demonstrated that SIX4 is important for the migration of osteosarcoma cells." (PMID 36601689, 2023). "We also utilized the human glucose metabolism PCR array to gain an in‐depth understanding of SIX4 for glycolysis in osteosarcoma." (PMID 36601689, 2023). "The expression profile of SIX4 in OS was evaluated in surgery samples of osteosarcoma patients." (PMID 36601689, 2023). "Therefore, we generated SIX4 overexpressing and knockdown cell lines to further explore the role and mechanisms of SIX4 in the pathogenesis of osteosarcoma." (PMID 36601689, 2023). "More importantly, higher SIX4 level predicts poorer outcomes of osteosarcoma patients." (PMID 36601689, 2023). "We found that SIX4 is required for the migration of osteosarcoma cells." (PMID 36601689, 2023). "Besides, the upregulation of SIX4 was correlated with increased expression of IDH1of osteosarcoma." (PMID 36601689, 2023). "However, the expression and functional role of SIX4 in osteosarcoma remains unknown." (PMID 36601689, 2023). "However, the role of SIX4 in osteosarcoma progression remains unknown." (PMID 36601689, 2023). "Altogether, upregulation of SIX4 altered glycolysis and transcriptionally activates IDH1 in osteosarcoma." (PMID 36601689, 2023). "SIX4 promotes progression of osteosarcoma via upregulating isocitrate dehydrogenase 1 (IDH1), which provides novel prognostic biomarkers and promising therapeutic targets for osteosarcoma patients." (PMID 36601689, 2023).
adenoma (1 paper, 2024). A neoplasm arising from the epithelium. "Targeting SIX4 alleviates intestinal inflammation occurrence and reduces adenoma formation in mice." (PMID 39309424, 2024). "Based on histomorphological analysis, we found that the use of si-SIX4 increased colon length in DSS-treated mice and reduced the number of adenomas induced by AOM+DSS." (PMID 39309424, 2024).
Esotropia (1 paper, 2021). A form of strabismus with one or both eyes turned inward ('crossed') to a relatively severe degree, usually defined as 10 diopters or more. "The results of RT-PCR revealed that PAX7, MYOG, PITX1, SIX1 and SIX4 showed higher levels of expression, while that of MYOD a lower level of expression within the paralytic esotropia group as compared with that in the control group (p < 0.05)." (PMID 34044792, 2021).
male infertility (1 paper, 2023). The inability of the male to effect fertilization of an ovum after a specified period of unprotected intercourse. "Thus, we wonder how to evaluate the regulatory mechanism between MKRN2 and STAT1/SIX4/TNC to figure out the novel mechanism of MKRN2 in male infertility." (PMID 36967804, 2023). "In this study, we found a new regulatory mechanism between MKRN2 and STAT1/SIX4/TNC, which is a novel mechanism of MKRN2 in regulating male infertility." (PMID 36967804, 2023). "In this study, we plan to address: (a) the role of MKRN2 in male infertility; (b) whether MKRN2 regulates the expression level of STAT1; and (c) how MKRN2 induces the expression levels of SIX4 and TNC by the transcription factor EBF transcription factor 2 (EBF2)." (PMID 36967804, 2023).
omphalocele (1 paper, 2018). Omphalocele is an embryopathy classified in the group of abdominal celosomias and is characterized by a large hernia of the abdominal wall, centered on the umbilical cord, in which the protruding viscera are protected by a sac. "Here, we report that mice doubly deficient in homeobox genes Six4 and Six5 showed the same ventral body wall closure defects as those seen in human omphalocele." (PMID 30237319, 2018). "Although all Six5−/− fetuses had no phenotypic changes in the ventral body (I′), a small number of Six4+/−;Six5−/− fetuses showed an enlarged umbilical ring or a small-type omphalocele (J′)." (PMID 30237319, 2018). "Therefore, we emphasize that Six4−/−;Six5−/− mice are a suitable animal model for large and small middle-type omphalocele reproducing typical human omphalocele." (PMID 30237319, 2018). "In the present study, we found that Six4−/−;Six5−/− mice show severe ventral body wall closure defects with few other anomalies, they have defects in PAW formation, and that omphalocele formation is in complete penetrance." (PMID 30237319, 2018). "We compared ventral body wall formation in Six4−/−;Six5−/− fetuses with large omphalocele and Six5−/− or Six4+/−;Six5+/− fetuses, which have no apparent defects in ventral body wall closure, at E15.5 and E18.5." (PMID 30237319, 2018). "As morphological differences in the PAW of other mutant mice that exhibit middle-type omphalocele have not been reported, analyses of Six4−/−;Six5−/− mice first revealed that the impaired morphogenesis of the PAW may lead to middle-type omphalocele." (PMID 30237319, 2018).
ovarian carcinoma (1 paper, 2015). A malignant neoplasm originating from the surface ovarian epithelium. "We found that miR‐124 has an extensive mRNA target space in ovarian epithelial cancer cells; however, suppression of the homeobox transcription factor SIX4 was sufficient to mimic the consequences of miR‐124 on ovarian cancer cell proliferation." (PMID 26655797, 2015). "Systemic delivery of siRNA targeting SIX4 effectively inhibited xenograft tumor growth, nominating SIX4 and/or SIX4 target genes as an ovarian cancer intervention target." (PMID 26655797, 2015).
ovarian tumors (1 paper, 2015). "Of note, increased SIX4 expression has been implicated in the suppression of tissue differentiation programs, and SIX4 is significantly overexpressed in ovarian tumors relative to normal ovarian tissue (Fig EV7D)." (PMID 26655797, 2015). "SIX4 is overexpressed in ovarian tumors relative to normal tissue and maintains cancer cell proliferation, at least in part, by supporting cyclin gene expression and suppressing AMPK pathway activation." (PMID 26655797, 2015).
tumor (14 papers, 2015 to 2024). "The reduction of SIX4-dependent tumor clearance was associated with decreased tumor infiltration of CD8+ T cells." (PMID 37888903, 2023). "Although we demonstrated that SIX4 is involved in inflammation tumor transformation, the underlying mechanism remains unclear." (PMID 39309424, 2024). "By observing the tumor-forming ratio, we found that SIX4 knockdown cell lines required higher population density to form tumor nodules." (PMID 39309424, 2024). "Tumorspheres assay and clonal formation assay showed that the knockdown of SIX4 decreased tumor spheres and clone formation." (PMID 39309424, 2024). "To further explore the mechanism of SIX4 involved in inflammation and tumor stemness, we compared the mice sequencing results (DSS vs NC and AOM+DSS vs NC) with the clinical sequencing results (IBD vs Normal, GSE186582) and screened out 609 differential genes." (PMID 39309424, 2024). "In summary, this study demonstrates a progressive upregulation of SIX4 expression, commencing in normal tissue, progressing through inflammatory tissue, and culminating in tumor tissue." (PMID 39309424, 2024). "Further analysis of bioinformatic and clinical data revealed a significant correlation between the expression of SIX4 and tumor recurrence." (PMID 39309424, 2024). "This tumor suppression activity of SIX4 adds an additional dimension to the SIX4 function during tumorigenesis." (PMID 37888903, 2023). "Given the importance of STING activation in the efficacy of anti-PD-1/PD-L1 therapies, we next determined the effect of SIX4 expression on the efficiency of an anti-PD-1 antibody-mediated inhibition of tumor growth in immune competent mice." (PMID 37888903, 2023). "The sine oculis homeobox 4 (SIX4) transcription factor, which belongs to the superfamily of homeobox gene family, has been identified contributes to tumour initiation, progression and metastasis." (PMID 36601689, 2023). "Our studies showed that SIX4 knockout tumors grew similarly as the control tumors with control IgG treatment, indicating that SIX4 expression by itself has insignificant effect on tumor growth in syngeneic mouse model." (PMID 37888903, 2023). "IHC staining of CD8 in tumor sections showed a marked reduction of CD8-positive T cells in the tumors of SIX4 knockout cells as compared with control tumors." (PMID 37888903, 2023). "Functional experiments in our study revealed that FOXA1 promoted CC cell resistance to DDP in vitro and facilitated tumor growth in vivo by upregulating SIX4 expression and activating the PI3K/AKT signaling." (PMID 35498155, 2022). "SIX4 has been lately revealed to indicate dismal clinical outcome of patients with esophageal squamous cell carcinoma and to potentiate tumor growth and cell metastasis." (PMID 35498155, 2022). "Following a 4‐week treatment regimen, SIX4 siRNA‐treated animals displayed significantly decreased total tumor weight and concomitantly reduced ascites." (PMID 26655797, 2015). "In addition, immunohistochemistry of tumor nodules showed that the knockdown of SIX4 decreased the expression of CD44 and CD133." (PMID 39309424, 2024). "Furthermore, the knockdown of SIX4 resulted in the inhibition of tumor stemness both in vivo and in vitro." (PMID 39309424, 2024). "Treatment with normal IgG in both control and SIX4 knockout tumors resulted in 100% tumor growth." (PMID 37888903, 2023). "Importantly, depletion of SIX4 significantly reduced efficacy of tumor clearance mediated by an anti-PD-1 antibody in syngeneic immune competent mice in vivo." (PMID 37888903, 2023). "However, anti-PD-1 treatment showed lower tumor clearance rate in SIX4 knockout group than in control group even though the treatment reduced tumor growth in both control and SIX4 knockout groups with tumors remaining." (PMID 37888903, 2023). "Previous studies have suggested that SIX4 function is correlated with tumor-promoting activity." (PMID 37888903, 2023).
tumor (continued). "Importantly, decrease of SIX4 expression substantially decreased tumor infiltration of CD8+ T cells and reduced the efficacy of PD-1 antibodies to diminish tumor growth in immune competent mice in vivo." (PMID 37888903, 2023). "SIX4 promoted tumor angiogenesis and metastasis via activating AKT pathway in CRC." (PMID 32351322, 2020). "Tumor responsiveness to SIX4 depletion in vivo was modeled using ES2 cell xenografts." (PMID 26655797, 2015). "However, the function of SIX4 in inflammation and tumor remains to be further investigated." (PMID 39309424, 2024). "Therefore, we speculated that SIX4 may be involved in the inflammation and tumor transformation by enhancing the stemness of tumor cells." (PMID 39309424, 2024). "Therefore, it is plausible that SIX4 may be involved in the regulation of tumor stemness as a transcription factor." (PMID 39309424, 2024). "Therefore, we speculated that SIX4 may contribute to tumor stemness through transcriptional regulation." (PMID 39309424, 2024). "Moreover, upregulation of SIX4 can promote ESCC tumor growth in vivo." (PMID 33481352, 2021). "Thus, silencing SIX4 inhibited tumor cell invasion and migration capacity." (PMID 28584719, 2017). "Therefore, we speculated that SIX4 may be related to tumor stemness." (PMID 39309424, 2024). "The top GRNs in primary tumors were TCF4, TAGLN2, FOXK1, and BHLHE41, whereas the top upregulated GRNs in recurrent tumor cells were FOXP2, FOXD1, SIX4, and HMGB1." (PMID 39711559, 2024). "In summary, we have identified SIX4 as a novel regulator of STING expression, which displays a tumor suppression function by increasing antitumor immunity." (PMID 37888903, 2023). "Taken together, these results indicate that depletion of SIX4 reduced CD8+ T-cell infiltration and attenuated tumor response to anti-PD-1 treatment." (PMID 37888903, 2023). "As expected, both ECAR/OCR and glucose consumption were upregulated when SIX4 is overexpressed, while downregulation of SIX4 spontaneously decreased the ECAR/OCR and glucose consumption of tumour cells." (PMID 36601689, 2023). "Knockout of SIX4 attenuated STING activator–mediated activation of STING/IFNβ signaling cascade and reduced efficacy of an anti-PD-1 antibody to eliminate tumor growth in immune competent mice." (PMID 37888903, 2023). "Upregulation of SIX4 indicates poor clinical outcomes in ESCC patients and promotes tumor growth and cell metastasis in ESCC." (PMID 33481352, 2021). "In addition, SIX4, STAT3, IL-6, SOX2, and C-JUN were upregulated in tumor spheres compared to adherent cells." (PMID 39309424, 2024). "Further, we observed that targeting SIX4 attenuated the transformation of inflammation to cancer in intestinal epithelium via inactivating IL-6/STAT3/SIX4/c-JUN feedback loop, which subsequently suppressed DeltaNp63-mediated tumor stemness signals." (PMID 39309424, 2024). "Taken together, these observations strongly suggest that tumor cells may evolve multiple mechanisms to escape SIX4’s upregulation of the STING pathway and tumor suppression function ultimately facilitating its tumor-promoting activity." (PMID 37888903, 2023). "Modulation of tumor differentiation may be attributed to HNF4α-mediated inhibition of mesodermal lineage markers SIX1 and SIX4 that are activated in the basal molecular subtype of PDAC21." (PMID 37974020, 2023). "Although depletion of SIX4 did not have a significant effect on tumor growth, it substantially reduced the response to anti-PD-1 treatment." (PMID 37888903, 2023). "In addition, SIX4 was found to activate AKT and promote tumor angiogenesis in solid tumor progression." (PMID 33481352, 2021). "More importantly, upregulation of SIX4 was found to promote ESCC tumor growth in vivo in this study, which has not been reported in previous studies." (PMID 33481352, 2021). "More importantly, upregulation of SIX4 could activate the PI3K/AKT pathway in ESCC cells and promote tumor growth in vivo." (PMID 33481352, 2021).
cancer (13 papers, 2015 to 2025). A tumor composed of atypical neoplastic, often pleomorphic cells that invade other tissues. "For instance, HF can inhibit the pro-survival AKT/STAT3 signaling in cancer cells to promote death, yet it activates the SIX4/AKT/STAT3 axis to protect hepatocytes from injury." (PMID 41511301, 2025). "In contrast, downregulation of CXCL12 and upregulation of SIX4, the two unique hub genes in MCF7-ERβ2 cells, are reportedly consistent with cancer-promoting effects and are linked to poor prognosis." (PMID 36835157, 2023). "Then, we analysed serious glycolysis‐related genes and found that IDH1 can be transcriptionally regulated by SIX4 to promote cancer cell migration." (PMID 36601689, 2023). "Sine oculis homeobox 4 (SIX4) is reported to be a key transcription factor that is involved in glycolysis reprogramming of cancer cells." (PMID 36601689, 2023). "The SIX4 expression levels in colorectal patients were assessed in nine different human cancer arrays and compared using patient survival data." (PMID 28584719, 2017). "Additionally, while HF exerts protection via SIX4/AKT/STAT3 activation, this pathway is also implicated in promoting tumor progression across various cancer types." (PMID 41511301, 2025). "The role of sine oculis homeobox 4 (SIX4) has been found in some malignant tumors." (PMID 33481352, 2021). "We have detected the expression of SIX4 in normal intestinal mucosa, IBD tissue, para-cancer tissue, and CRC tissue." (PMID 39309424, 2024). "Overall, inhibition of SIX4 expression in IBD and CAC models demonstrated a reduction in inflammation and the transformation of inflammation into cancer." (PMID 39309424, 2024). "Results indicate a significant upregulation of SIX4 in IBD and CRC tissues, when compared to normal mucosa and para-cancer tissues, respectively." (PMID 39309424, 2024). "In this context, it should be noted that SIX1 and SIX4 contribute to the regulation of metastasis and EMT in cancer cells." (PMID 30237319, 2018). "However, the mechanisms that SIX4 may regulate in cancer progression remained unclear." (PMID 28584719, 2017). "However, the role and mechanism of SIX4 in IBD as well as the transformation of inflammation to cancer have not been reported." (PMID 39309424, 2024). "Moreover, cancer cells that survived the anti-PD-1 treatment probably developed escaping mechanism(s) and continued to grow regardless of SIX4 expression." (PMID 37888903, 2023).
infection (2 papers, 2015 to 2022). The state of being infected such as from the introduction of a foreign agent such as serum, vaccine, antigenic substance or organism. "Interestingly, Six4 is required for full virulence of an Arabidopsis-infecting Fo strain: infection assays with a SIX4 deletion strain showed reduced disease symptoms and reduced fungal biomass compared to the wild-type strain Fo5176." (PMID 26473835, 2015).
intestinal diseases (1 paper, 2023). "Several of these genes, including Ralbp1, Pfas, Tyro3, Opcml, Syne2, Six4, Tll2, and Slc23a2, were previously implicated in gut microbiome abundance, metabolic traits, and several intestinal diseases." (PMID 37420306, 2023).
SIX4 also shares sentences with these, for which no sentence is quoted: glioblastoma multiforme (3 papers); leukaemia (2); pancreatic ductal adenocarcinoma (2); cervical cancer (1); colitis (1); depression (1); glioma (1); hypogonadotropic hypogonadism (1); inflammatory bowel disease (1); Insulin resistance (1); melanoma (1); teratozoospermia (1).